ENSG00000277971 (novel protein)
Gene: Protein-coding gene on chromosome 22 (20,429,241 to 20,446,620, reverse strand). Ensembl gene ENSG00000277971.
Genetic constraint (gnomAD): Missense variants: 60 observed, 85.4 expected, observed/expected ratio (o/e) 0.7, 90% interval 0.57 to 0.87. Synonymous variants: 43 observed, 35.5 expected, observed/expected ratio (o/e) 1.21, 90% interval 0.95 to 1.56.